RAB30 (RAB30, member RAS oncogene family)
Description:
The small GTPases Rab are key regulators of intracellular membrane trafficking, from the formation of transport vesicles to their fusion with membranes. Rabs cycle between an inactive GDP-bound form and an active GTP-bound form that is able to recruit to membranes different sets of downstream effectors directly responsible for vesicle formation, movement, tethering and fusion. RAB30 is required for maintaining the structural integrity of the Golgi apparatus, possibly by mediating interactions with cytoplasmic scaffolding proteins. Facilitates lipid homeostasis during fasting by regulating hepatic protein and lipid trafficking in a PPAR-alpha-dependent manner (By similarity). Promotes autophagosome biogenesis during bacterial infection such as group A Streptococcus infection.
Tractability: Small molecule: a structure with a bound ligand is known. PROTAC: ubiquitination databases record sites on it; its protein half-life has been measured.
Gene: Protein-coding gene on chromosome 11 (82,973,133 to 83,071,923, reverse strand). Ensembl gene ENSG00000137502.
Subcellular location: Membrane; Golgi apparatus, trans- Golgi network membrane; Golgi apparatus, cis-Golgi network membrane; Golgi apparatus membrane; Cytoplasm; Cytoplasmic vesicle, autophagosome membrane; Autolysosome membrane
Subcellular location (Human Protein Atlas): Vesicles
Pathways (Reactome):
Metabolism of proteins: RAB geranylgeranylation
Vesicle-mediated transport: Intra-Golgi traffic
Gene Ontology:
Molecular function: G protein activity; GTPase activity; protein binding; GTP binding
Biological process: Golgi organization; lipid homeostasis; Rab protein signal transduction
Cellular component: autolysosome membrane; autophagosome membrane; cis-Golgi network; cis-Golgi network membrane; cytoplasm; Golgi cisterna; Golgi membrane; trans-Golgi network; Golgi stack; bounding membrane of organelle; Golgi apparatus; membrane
Genetic constraint (gnomAD): Loss-of-function variants: 8 observed, 22.25 expected, observed/expected ratio (o/e) 0.36, 90% interval 0.21 to 0.65. The upper end of that interval is the gene's LOEUF score, 0.65, which puts it in group 2 of 6, group 1 being the genes least tolerant of losing a copy. Missense variants: 135 observed, 244.81 expected, observed/expected ratio (o/e) 0.55, 90% interval 0.48 to 0.64. Synonymous variants: 73 observed, 88.44 expected, observed/expected ratio (o/e) 0.83, 90% interval 0.68 to 1.
Homologues: Orthologues: chimpanzee RAB30 (100% identical), dog RAB30 (100% identical), guinea pig RAB30 (100% identical), macaque RAB30 (100% identical), mouse Rab30 (100% identical), pig RAB30 (100% identical), rabbit RAB30 (100% identical), rat Rab30 (100% identical), tropical clawed frog rab30 (93% identical), zebrafish rab30 (85% identical), Drosophila melanogaster Rab30 (66% identical), Caenorhabditis elegans rab-30 (56% identical). Paralogues in human: RAB43 (53% identical), RAB19 (48% identical), RAB8B (43% identical), RAB10 (42% identical), RAB35 (42% identical), RAB1A (42% identical), RAB1B (42% identical), RAB33A (42% identical), RAB2B (41% identical), RAB8A (41% identical), RAB12 (40% identical), RAB4A (40% identical), and 56 more.
Diseases named in the same sentence as RAB30 in open-access papers:
RAB30 is named in the same sentence as 13 diseases in open-access papers, as found by Europe PMC text mining. Sharing a sentence is not in itself a finding about the gene and the disease. The quoted sentences say what the papers report.
breast carcinoma (1 paper, 2019). "In silico analysis of breast cancer clinical datasets showed that KLK6 expression inversely correlates with RAB26, RAB17, and RAB30." (PMID 30980596, 2019).
dyslipidemia (1 paper, 2024). "The loss of Rab30 on the Cpt2L−/− background also reverses serum dyslipidemia and hypercholesterolemia in the Cpt2L−/− knockout mice." (PMID 38796472, 2024). "Rab30 whole-body, liver-specific, and Rab30; Cpt2 liver-specific double knockout (DKO) mice are viable with intact Golgi ultrastructure, although Rab30 deficiency in DKO mice suppresses the serum dyslipidemia observed in Cpt2L−/− mice." (PMID 38796472, 2024). "Rab30 is highly induced in the liver of Cpt2L−/− mice that cannot perform hepatic β-oxidation and therefore exhibit fasting-induced hepatic steatosis, serum dyslipidemia, and increased Pparα transcriptional activity." (PMID 38796472, 2024). "Loss of Rab30 in the Cpt2L−/− liver rescues the dyslipidemia and serum cholesterol levels, without altering hepatic triglyceride content." (PMID 38796472, 2024).
Hypercholesterolemia (1 paper, 2024). An increased concentration of cholesterol in the blood. "Loss of Rab30 affects the flux of secreted hepatic proteins and prevents hypertriglyceridemia and hypercholesterolemia in the pathologically fatty livers of fasted mice that cannot oxidize fat." (PMID 38796472, 2024).
cancer (3 papers, 2020 to 2022). A tumor composed of atypical neoplastic, often pleomorphic cells that invade other tissues. "We found that 30 of these genes which included Nckap1l, Ncf1, Pla2g15, Unc93b1, Lrrc33, Rgs10, Gmfg, Rbm25, C3ar1, Ccdc88b, Fam105a, Gng11, Phc1, Rasa4, Dag1, Tyrobp, Tmsb4x, Cfp, Prkd1, Gp49a, Trem2, C1qc, Lyz2, Igfbp7, Rab30, Cxcl16, Egfl7, Ube2r2, Pltp, and Cfb, showed a relation with cancer." (PMID 32812032, 2020).
tumor (3 papers, 2013 to 2026). "Five variables (LINC01089, RGS11, MXD3, BIRC5, and RAB30) of Sig27var25 are risk factors of poor OS and three of them remain risk factors of fatality after adjusting for age at diagnosis and tumor stages." (PMID 35681785, 2022). "Among the upregulated genes, we identified several oncogenes (Ets2, Fyn, Fos, Rab30 and Src), various tumor markers (Cyp1b1, Gpa33, Cd47, Fam129a, st7l, chka, Lgalsbp, Antxr1 and Ly6a) and other genes related to tumor promotion (Cxcl10, Trim25, Grn, Foxc2, Bmp7 and Irs1)." (PMID 23936067, 2013). "Sig27var25 and SigIQvar8 are highly effective at predicting ACC prognosis and progression; both signatures contain component genes predicting poor OS independently of age and tumor stages, for instance SNHG10 and RECQL4 for SigIQvar8 as well as MXD3, BIRC5, and RAB30 for Sig27var25." (PMID 35681785, 2022). "We found that the correlation of expression for CLIC6 and RAB30 in neighboring cells is higher in the ER+/PR+ group, while the correlation of expression for KLRD1 and LTB is higher in the ER‐/PR‐ group, regardless of whether the tumor is detected in the early or late stage." (PMID 40420636, 2026).
infection (2 papers, 2016 to 2020). The state of being infected such as from the introduction of a foreign agent such as serum, vaccine, antigenic substance or organism. "Several other Rabs displaying close phylogenetic relationship to Rab1, including Rab8, Rab18, Rab35, Rab33, Rab30, Rab19, and Rab37, could also be modified by SseK3 upon infection." (PMID 32504010, 2020). "However, neither the involvement of Rab30 in autophagy nor the functions of Rab30 during pathogenic infection have not been addressed." (PMID 26771875, 2016). "Although Rab30 knockdown did not affect GAS invasion, the survival rate of GAS at 6 h post-infection was significantly higher in Rab30-knockdown cells than in control cells." (PMID 26771875, 2016).
bacterial infection (1 paper, 2016). "Thus, identifying the GEF and GAP for Rab30 would be informative in understanding how host cells respond to bacterial infection and regulate autophagic vacuole formation." (PMID 26771875, 2016).
RAB30 also shares sentences with these, for which no sentence is quoted: asthma (1 paper); cervical cancer (1); colorectal cancer (1); Hepatic steatosis (1); hypertriglyceridemia (1); steatosis (1).